FST (follistatin)
Diseases named in the same sentence as FST in open-access papers (continued):
Sharing a sentence is not in itself a finding about the gene and the disease.
prostate carcinoma (12 papers, 2000 to 2023). A carcinoma that arises from epithelial cells of the prostate gland. "Follistatin neutralizes activin-mediated suppression of prostate cell growth; furthermore, follistatin levels in men with prostate cancer have been associated with increased risk of bone metastasis." (PMID 24305501, 2014). "FST has a high affinity for activin A, and increasing evidence reveals that dysregulation of the FST/activin A system could lead to alterations of the normal homeostasis of prostate tissue and cause development and progression of prostate cancer." (PMID 36608258, 2023). "In support of the previous suggestion, in vitro studies on prostate cancer have revealed that the progression of tumour and development of resistance to the growth inhibitory actions of activin-A were associated with higher levels of follistatin." (PMID 27835986, 2016). "In order to ascertain the broader applicability of these findings, we interrogated the role of FST in other prostate epithelial (BPH‐1) or prostate cancer (DU145, LNCaP and 22RV1) cell lines." (PMID 36608258, 2023). "Overexpression of FST was found in several human tumors, including gastric cancer, ovarian cancer, prostate cancer, basal cell carcinoma and hepatocellular carcinoma." (PMID 30377409, 2018). "We analyzed 14 additional genes, including the AR-activated genes PSA, FKBP51, ORM1, STAG, Nkx3.1, FASN, AQP3, KLK2, and UGT2B; the AR-repressed genes DKK and FST; and the castration-resistant prostate cancer AR-regulated genes CDC20, CDK1, and UBE2C." (PMID 22761715, 2012). "The activin and follistatin balance has been shown to be dysregulated in numerous solid tumors, such as prostate cancer and hepatocarcinogenesis and the development of resistance to TGFβ growth inhibition is a key event in tumor progression." (PMID 19558675, 2009). "Follistatin, which bioneutralises activin A, was validated as a key factor required for fibroblasts to promote prostate cancer cell proliferation and migration in vitro, and for xenograft growth from co‐culture grafts, and therefore represents a potential therapeutic target." (PMID 36608258, 2023). "In summary, these results indicate that a marked increase in FST production occurs when prostate cancer cells are co‐cultured with prostate fibroblasts, both cell types generate functional FST and this factor promotes both proliferation and migration of co‐cultured prostate cancer cells." (PMID 36608258, 2023). "This study highlights the complexity of prostate cancer cell–fibroblast communication, demonstrates that co‐culture secretomes cannot be predicted from individual cultures, and identifies FST as a tumour‐microenvironment‐derived secreted factor that represents a candidate therapeutic target." (PMID 36608258, 2023). "Furthermore, our findings might be relevant for the osteolytic bone metastasis formation of other tumor entities as well, as we could show the regulation of NOG and FST by ZEB1 in the prostate cancer cell line DU145." (PMID 25973542, 2015). "Depletion of ZEB1 in the prostate cancer cell line DU145, which is known to form osteolytic bone metastases, again decreased the expression of NOG mRNA and protein, as well as FST." (PMID 25973542, 2015). "TMEFF2 is a type I transmembrane protein with two follistatin (FS) and one EGF‐like domain over‐expressed in prostate cancer; however its biological role in prostate cancer development and progression remains unclear, which may, at least in part, be explained by its proteolytic processing." (PMID 28762604, 2018).
muscular dystrophy (10 papers, 2009 to 2025). Muscular dystrophy (MD) refers to a group of more than 30 genetic diseases characterized by progressive weakness and degeneration of the skeletal muscles that control movement. "Gene therapy or recombinant protein delivery of FST has shown significant efficacy in treating muscle atrophy and muscular dystrophy, and it promotes myocyte proliferation through the activation of the PI3K/Akt/mTOR signaling pathway." (PMID 40504789, 2025). "Concerning follistatin, the pivotal function of this protein is the inhibition of the myostatin pathway in order to regulate the muscle mass in muscular dystrophies." (PMID 32961888, 2020). "Intriguingly, histone deacetylase inhibitors or nitric oxide have been demonstrated to inhibit the progression of muscular dystrophy in a mouse model by transcriptional activation of FST." (PMID 19538713, 2009). "On the other hand, in a study conducted in mice with induced muscular dystrophy, the inhibition of myostatin through the expression of the follistatin transgene resulted in early improvements in histopathology, but, in the long term, muscle degeneration increased." (PMID 38893612, 2024). "Indeed, studies of muscular dystrophy in mouse models using human recombinant FST or the human FST transgene show cross-species activity between human FST and mouse tissues." (PMID 38392348, 2024). "Inhibition of myostatin- and activin-mediated SMAD2/3 signaling using ligand traps, such as soluble receptors, ligand-targeting propeptides and antibodies, or follistatin can increase skeletal muscle mass in healthy mice and ameliorate wasting in models of cancer cachexia and muscular dystrophy." (PMID 33250771, 2020). "23, follistatin overexpression improves tissue repair after muscle injury, and follistatin-based therapeutic interventions have shown signs of beneficial regenerative activity in preclinical models of muscular dystrophy or in preliminary clinical studies." (PMID 31388039, 2019). "Hence, this is consistent with a bona fide cure of muscular dystrophy in this preclinical model when the next-generation AAV9 vectors that expressed the MD1 and FST genes from the de novo designed SkCRM4-Des promoter." (PMID 30700722, 2019).
polycystic ovary syndrome (10 papers, 2011 to 2025). A disorder that manifests as multiple cysts on the ovaries. "Dysregulated follistatin expression has been implicated in reproductive disorders such as polycystic ovary syndrome (PCOS) and premature ovarian insufficiency." (PMID 40777786, 2025). "For example, FST encodes the adipokine follistatin which has been shown to regulate adipocyte differentiation and is also a marker of polycystic ovary syndrome (PCOS)." (PMID 36434155, 2023). "For example, human polycystic ovarian syndrome (PCOS) is associated with low serum concentration of activin and high concentration of follistatin." (PMID 36469526, 2022). "This meta-analysis was performed to resolve the inconsistencies regarding resistin and follistatin levels in women with polycystic ovary syndrome (PCOS) by pooling the available evidence." (PMID 33740002, 2021). "Linkage studies of 37 candidate genes predicted strong association of follistatin and nominal association of CYP11A1 gene in affected siblings with hyperandrogenemia and PCOS related traits." (PMID 29670770, 2018).
diabetes (8 papers, 2016 to 2025). "In this study, we observed that plasma follistatin levels were elevated many years prior to the onset of T2D, and that circulating follistatin at baseline associated with incident T2D, independently of established diabetes risk markers." (PMID 34759311, 2021). "In the MDC-CC cohort, elevated plasma follistatin levels associated with the incidence of diabetes up to 19 years before the onset of the disease." (PMID 34759311, 2021). "In conclusion, elevated circulating follistatin associates with an increased risk of incident T2D, independently of established diabetes risk markers." (PMID 34759311, 2021). "The independent association between the elevated follistatin and an increased risk of diabetes was also confirmed in this shorter follow-up period." (PMID 34759311, 2021). "Activin A and follistatin levels were elevated in diabetic patients, but only elevated activin A was an independent risk factor for prediabetes and diabetes after adjustment for the available confounders." (PMID 29967428, 2018). "So far it is unknown whether elevation of plasma follistatin associates with the risk of T2D, independently of established diabetes risk markers." (PMID 34759311, 2021). "Circulating follistatin associated with an elevated risk of diabetes, hazard ratio (HR) per 1-SD increase in follistatin levels for T2D is 1.29 (CI: 1.19–1.40, p < 0.001), adjusted for age and sex; and 1.24 (CI: 1.04–1.47, p < 0.05) adjusted for multiple risk factors." (PMID 34759311, 2021). "Our study suggests that potential applications of Follistatin may be expanded and further investigation of Follistatin as local and potential systemic treatment of diabetes and diabetes associated bony defects are warranted." (PMID 28852138, 2017). "While it is important that this association was found during a long period of follow-up, parameters other than elevated follistatin levels, which may become relevant just prior to the onset of diabetes, or also associate with elevated follistatin levels, may contribute to this relationship." (PMID 34759311, 2021). "The HRs per SD of plasma follistatin for diabetes was 1.35 (CI: 1.13–1.61, p < 0.01) adjusted for age, and 1.31 (CI: 1.09–1.58, p < 0.01) adjusted for multiple risk factors." (PMID 34759311, 2021). "In obese individuals with diabetes who underwent gastric bypass surgery, serum follistatin decreased in parallel with HbA1c levels." (PMID 34759311, 2021). "This community-based study was conducted to clarify the roles of activin A and follistatin in prediabetes and diabetes, and to explore the relationship between these levels and carotid intima-media thickness (cIMT), a surrogate marker of atherosclerosis." (PMID 29967428, 2018). "Diabetes-related elevations in circulating TNFa, GROa, and follistatin have been reported previously." (PMID 27453994, 2016). "When subjects were divided into quartiles (Q) based on plasma follistatin level, the HRs adjusted for age and sex for Q4 vs. Q1 for incident diabetes was 1.97 (CI: 1.55–2.50, p for trend < 0.001); and 1.35 (CI: 1.04–1.74, p for trend = 0.02) adjusted for multiple risk factors." (PMID 34759311, 2021). "Individuals with diabetes incidence had higher baseline plasma follistatin levels." (PMID 34759311, 2021). "In the logistic regression model adjusted for other risk factors, the serum follistatin concentration was not an independent risk factor for diabetes." (PMID 29967428, 2018). "We thus speculate that the complex roles of activin A and follistatin in the development of prediabetes and diabetes resemble those reported for NAFLD." (PMID 29967428, 2018). "However, it is worth noting that our C-statistics analysis also suggests that follistatin on its own may not improve diabetes prediction beyond established risk factors." (PMID 34759311, 2021).
diabetes (continued). "We also included fasting glucose and CRP to the models to ensure that factors in the subclinical phase of diabetes development were not responsible for the raised levels of follistatin." (PMID 34759311, 2021). "Subjects who developed T2D during follow-up had higher plasma follistatin levels at baseline, compared to those who did not progress to diabetes." (PMID 34759311, 2021). "Patients with diabetes had significantly enhanced follistatin concentrations compared with those with prediabetes and normal glucose levels." (PMID 29967428, 2018). "In this study, we found that circulating concentrations of activin A and follistatin are elevated in patients with diabetes independent of demographic parameters." (PMID 29967428, 2018). "However, the lack of correlation between cIMT and activin A or follistatin in subjects with diabetes requires explanation." (PMID 29967428, 2018). "The correlation between follistatin and cIMT was also significant in the normal glycemic (n = 205; rs = 0.221, p = 0.001) and prediabetes (n = 164; rs = 0.271, p < 0.001) groups, but not in the diabetes group (n = 83)." (PMID 29967428, 2018).
hepatocellular carcinoma (8 papers, 2013 to 2024). A malignant tumor that arises from hepatocytes. "In melanoma, prostate and hepatocellular carcinoma, a mechanism underlying the resistance to the growth inhibitory effect of ActA is FST overexpression." (PMID 26950277, 2016). "Imbalanced expression of follistatins in hepatoma cells is a well-known event, and it has been suggested that FST expression is required for proliferation and colony expansion of progenitor populations of hepatocytes." (PMID 32610656, 2020). "Serum FST levels were correlated not only with pregnancy but also with various solid tumors, including gonadal cancer, gastric cancer, hepatocellular carcinoma, basal cell carcinoma, and melanoma." (PMID 30377409, 2018). "Imbalanced expression of follistatins and activins in preneoplastic foci and hepatoma cells is well known and some researchers suggest follistatin expression is required for proliferation and colony expansion of progenitor populations of hepatocytes." (PMID 23630614, 2013). "Overexpression of FST has been found in melanoma, prostate cancer and hepatocellular carcinoma." (PMID 26950277, 2016). "Hence, it has been suggested that pathological alteration in the hepatic expression of activin and follistatin could lead to impaired liver regeneration and the development of liver fibrosis, cirrhosis, and hepatocellular carcinoma." (PMID 24799891, 2014). "Possible cells producing follistatin in a negative feedback loop as an answer to activin A are liver cells as shown for the human hepatocellular carcinoma cell line HepG2." (PMID 31182152, 2019).
melanoma (8 papers, 2014 to 2024). A malignant, usually aggressive tumor composed of atypical, neoplastic melanocytes. "Indeed, FST is consistently found to be secreted by solid tumors, including melanomas, ovarian adenocarcinomas, and lung adenocarcinomas, and its expression exhibits a notable upregulation when compared to normal tissue samples." (PMID 38392348, 2024). "Conversely, FST has also been found to bolster anti-tumor immunity and block metastasis by inhibiting activin-A signaling in tumor-resident natural killer cells in an orthotopic melanoma mouse model." (PMID 38392348, 2024). "Similarly, genes related to melanoma invasion were downregulated in SIRT2-deficient melanoma cell lines (e.g., HLA-DRA, IL-6, CD74, and HLA-DRB1 in the SSW30 clone, Dataset S1; PTPRZ1, FST, and NRCAM in the SSM15 clone, Dataset S2)." (PMID 31091806, 2019). "However, treating TGF-βRII-deleted mice with melanoma with follistatin could further reduce melanoma lung metastasis, indicating that activin A functioned independently from TGF-β." (PMID 35774793, 2022). "In HUVECs co-cultured with melanoma cells there was a marked decrease in expression levels of several endothelial markers (KRT7, KRT18, TJP2), as well as a severe decrease in FST expression, an EMT/EndMT antagonist." (PMID 25742314, 2015). "CD271 knockdown was found to eliminate the capacity of melanoma cells to form heterogeneous tumors most likely through the downregulation of mediators for melanoma invasion and metastasis (GLI-2, SOX2 and ERBB3), angiogenesis (IGFBP-2), proliferation (FST and MITF) or chemoresistance (RHOJ)." (PMID 25351876, 2015).
COVID-19 (7 papers, 2022 to 2025). A disease caused by infection with severe acute respiratory syndrome coronavirus 2. "Increased plasma levels of Follistatin have been associated with in-hospital mortality of COVID-19 patients as well and were shown to be predictive of the fatal outcome at any time of the disease progression." (PMID 38476229, 2024). "The identification of altered biomarkers such as osteocalcin, PINP, ALP, OPN, COMP, HA, IGF-1, myostatin, follistatin, and creatine kinase can provide a foundation for developing minimally invasive diagnostic tools to detect early bone, cartilage, and muscle involvement in COVID-19 patients." (PMID 40943488, 2025). "In acute COVID-19 pathophysiology, the activin/follistatin axis is perturbed, with follistatin acting as a key counter-regulator of heightened activin signaling." (PMID 40943488, 2025). "Serum levels of activin A, activin B, and follistatin are markedly increased in COVID-19 patients; the levels corelate with disease severity and in-hospital mortality." (PMID 35307018, 2022). "Similarly, muscle-related biomarkers, including IGF-1, myostatin, follistatin, and creatine kinase further highlight the profound impact of COVID-19 on skeletal muscle mass, function, and recovery potential." (PMID 40943488, 2025).
liver fibrosis (7 papers, 2013 to 2025). "Our results suggest that HCV and/or its associated liver fibrosis modulated serum activin-A and follistatin." (PMID 24799891, 2014). "The activin–follistatin axis is indeed recognized as a critical node in the regulation of the inflammatory response and the progression of liver fibrosis through modulation of the TGF-β1 signaling pathway." (PMID 40647228, 2025). "Follistatin, which is broadly secreted by the liver, plays a role in the inhibition of activins or myostatins, a process that disrupts muscle growth; additionally, follistatin induces a pro-inflammatory state that promotes liver fibrosis and IR." (PMID 39796612, 2025). "Follistatin has opposing activity to activins/myostatin in fibrosis; attenuating early liver fibrosis, and lung fibrosis in murine models." (PMID 28769795, 2017). "Specifically, a previous study demonstrated that follistatin, a natural antagonist of Activin A, attenuated the progression of liver fibrosis via controlling the Activin A inducible HSC activation and hepatocyte apoptosis." (PMID 27011166, 2016). "In a separate animal model, follistatin attenuated fibrosis in CCl4-induced hepatic fibrosis as determined by histochemical staining and by hydroxyproline content." (PMID 24204752, 2013). "Activin A is also implicated in the stimulation of fibrosis in a range of experimental models and this action can be inhibited by its binding protein, follistatin; for instance, in a model (carbon tetrachloride (CCl4) -induced) of hepatic fibrosis or bleomycin induced pulmonary fibrosis." (PMID 24204752, 2013).